CD180 (CD180 molecule)
Description:
Pattern recognition receptor predominantly expressed on B-cells, dendritic cells, and certain monocytes/macrophages, structurally resembling Toll-like receptors (TLRs) that plays a role in modulating immune responses. While ressembling a TLR, lacks the intracellular TIR (Toll/IL-1R) signaling domain and thus does not directly transduce signals. Instead, modulates immune responses, often in conjunction with other TLRs. For example, in cooperation with MD-1/LY86, interacts directly with the TLR4 signaling complex, inhibiting its ability to bind microbial ligand.
Synonyms: LY64; RP105; Ly78
Tractability: Antibody: its Gene Ontology location is reachable by antibodies, with high confidence; UniProt places it where antibodies can reach, with medium confidence; UniProt predicts a signal peptide or a membrane-spanning region. PROTAC: ubiquitination databases record sites on it; its protein half-life has been measured.
Gene: Protein-coding gene on chromosome 5 (67,179,613 to 67,196,799, reverse strand). Ensembl gene ENSG00000134061.
Subcellular location: Cell membrane
Subcellular location (Human Protein Atlas): Plasma membrane; Mitotic spindle; Nucleoli; Nucleoplasm
Pathways (Reactome):
Immune System: Toll Like Receptor 4 (TLR4) Cascade
Gene Ontology:
Molecular function: lipopolysaccharide immune receptor activity; protein binding; signaling receptor activity
Biological process: positive regulation of lipopolysaccharide-mediated signaling pathway; B cell proliferation; B cell proliferation involved in immune response; cellular response to lipopolysaccharide; lipopolysaccharide-mediated signaling pathway
Cellular component: plasma membrane
Genetic constraint (gnomAD): Loss-of-function variants: 10 observed, 7.63 expected, observed/expected ratio (o/e) 1.31, 90% interval 0.79 to 1.89. That is too few expected variants to judge how well the gene tolerates losing a copy. Missense variants: 669 observed, 750.98 expected, observed/expected ratio (o/e) 0.89, 90% interval 0.83 to 0.95. Synonymous variants: 266 observed, 291.61 expected, observed/expected ratio (o/e) 0.91, 90% interval 0.82 to 1.01.
Homologues: Orthologues: chimpanzee CD180 (99% identical), macaque CD180 (94% identical), pig CD180 (78% identical), dog CD180 (77% identical), rat Cd180 (74% identical), mouse Cd180 (74% identical), rabbit CD180 (74% identical), guinea pig CD180 (74% identical), zebrafish cd180 (38% identical). Paralogues in human: TLR7 (23% identical), NRROS (23% identical), TLR8 (22% identical), TLR3 (22% identical), TLR4 (20% identical), LRRC32 (20% identical), TLR5 (20% identical), IGFALS (20% identical), TLR6 (19% identical), TLR2 (18% identical), TLR1 (17% identical), TLR10 (17% identical), and 10 more.
Diseases named in the same sentence as CD180 in open-access papers:
CD180 is named in the same sentence as 49 diseases in open-access papers, as found by Europe PMC text mining. Sharing a sentence is not in itself a finding about the gene and the disease. The quoted sentences say what the papers report.
systemic lupus erythematosus (7 papers, 2018 to 2023). An autoimmune multi-organ disease typically associated with vasculopathy and autoantibody production. "Differential expression of CD180 was associated with other rheumatic diseases, such as systemic sclerosis, systemic lupus erythematosus, and Sjögren’s syndrome." (PMID 38187379, 2023). "What's more, treatment of anti-CD180 Ab efficiently ameliorated the lupus-symptoms of lupus-prone mice." (PMID 30498494, 2018). "Collectively, all these data suggest that ligation of CD180 by anti-CD180 Ab show an efficient treatment effect on lupus-like symptoms in IMQ-mice." (PMID 30498494, 2018). "In lupus CD180-negative B cells have been described as highly activated and CD180 can be internalised after stimulation, indicating that CD180-negative B cells may result from B cell activation via CD180." (PMID 36726987, 2022). "What's more, injection of anti-CD180 Ab could markedly ameliorate the lupus-symptoms of imiquimod-treated mice and lupus-prone MRL/lpr mice through inhibiting the activation of macrophages and DCs." (PMID 30498494, 2018). "What's more, we also noted that ligation of CD180 could significantly relieve the lupus-symptoms of IMQ-treated mice and MRL/lpr mice." (PMID 30498494, 2018). "We found that injection of anti-CD180 Ab could markedly relieve the lupus-symptoms of IMQ-treated mice and MRL/lpr mice." (PMID 30498494, 2018). "Since our earlier data showed that ligation of CD180 can negatively regulate TLR7- and TLR9-mediated activation of macrophages and DCs in vitro, we guess that ligation of CD180 may inhibit the activation of macrophages and DCs in vivo, and relieve the symptoms of lupus-prone mice." (PMID 30498494, 2018). "Collectively, all these data indicate that CD180-negative macrophages and DCs are both increased in lupus-prone MRL/lpr mice and CD180 expression were negatively correlated with the activation of macrophages and DCs." (PMID 30498494, 2018). "Ligation of CD180 inhibits TLR7- and TLR9-mediated activation of macrophages and DCs through the Lyn-SHP-1/2 axis, and subsequently relieves the lupus-symptoms of lupus-prone mice." (PMID 30498494, 2018). "CD180-negative B cells were increased in patients with Sjögren's syndrome and in systemic lupus erythematosus (SLE) patients." (PMID 34124274, 2021). "The severity of the disease in systemic lupus erythematosus (SLE) patients correlated with the amount of CD180-negative B cells in the peripheral blood." (PMID 31817576, 2019). "The data presented in this paper demonstrated that CD180, low-expressed in macrophages and DCs from SLE patients and lupus-prone MRL/lpr mice, could negatively regulate TLR7- and TLR9-mediated activation of macrophages and DCs in vivo and in vitro." (PMID 30498494, 2018). "Furthermore, increased proportions of CD180-negative B cells correlate with increased renal legions in murine lupus-like nephritis models and CD180-negative SLE B cells are primarily responsible for the production of anti-double stranded DNA autoantibodies." (PMID 37460961, 2023). "As expected, injection of anti-CD180 Ab could significantly reduce the levels of CD86 on peritoneal macrophages, splenic macrophages and DCs from MRL/lpr mice, indicating that ligation of CD180 can inhibit the activation of macrophages and DCs in vivo and ameliorates lupus-symptoms in MRL/lpr mice." (PMID 30498494, 2018). "CD180-negative B cells, macrophages, and dendritic cells were shown to be elevated in SLE and in lupus-prone mice." (PMID 31817576, 2019). "As the percentages of CD180-negative macrophages and DCs were both increased in SLE patients and lupus-prone MRL/lpr mice, it is curious to explore the influencing factors which can induce the differentiation of these populations." (PMID 30498494, 2018).
autoimmune disease (5 papers, 2018 to 2024). A disorder resulting from loss of function or tissue destruction of an organ or multiple organs, arising from humoral or cellular immune responses of the individual to their own tissue constituents. "This concept aligns with the studies of CD180 in autoimmune disease where loss of CD180 tends to be associated with a more severe disease phenotype (see section on CD180 in disease)." (PMID 37460961, 2023). "Distinct expression and functions of CD180 on B cells have been associated with infection, chronic inflammation, and autoimmune diseases." (PMID 34124274, 2021). "Differential expression and functions of CD180 on B cells have been associated with immune-mediated pathologies, including infection, chronic inflammation, and autoimmune disorders." (PMID 31817576, 2019). "Altered expression and function of the Toll-like receptor (TLR) homologue CD180 molecule in B cells have been associated with autoimmune disorders." (PMID 31817576, 2019). "rs6890674 is located in the 3′ untranslated region of CD180, an orphan Toll-like receptor that is expressed on B cells and is involved in inflammatory and autoimmune diseases." (PMID 38836758, 2024). "We then discuss the role of CD180 in inflammatory and autoimmune diseases, as well as in hematological malignancies of B cell origin, including chronic lymphocytic leukemia (CLL)." (PMID 37460961, 2023). "We discuss the role of CD180 in hematological malignancies, autoimmune diseases, and other inflammatory diseases." (PMID 37460961, 2023). "The altered expression and functions of CD180 in B cells have been described in autoimmune diseases." (PMID 34124274, 2021). "Decreased expression of TLR homolog CD180 in peripheral blood B cells and its potential role in antibody production have been described in autoimmune diseases." (PMID 34124274, 2021). "Notably, CD180 tends to be downregulated in hematological malignancies, autoimmune diseases, and some inflammatory conditions which therefore suggests that CD180 promotes health." (PMID 37460961, 2023). "Since it was described in other autoimmune diseases that differential expression of CD180 (RP105) might have a pathological role in B cell activation and autoantibody production, first we determined the CD180 expression of monocytes, T cells, and B cells." (PMID 31817576, 2019). "CD180 has been extensively studied within the context of autoimmune disease and other non-malignant inflammatory disorders where it appears to play a pathophysiological role." (PMID 37460961, 2023).
chronic lymphocytic leukemia (4 papers, 2021 to 2023). "Previously, we reported decreased expression of CD180 in the B cells of dcSSc patients, and CD180 was described to utilize the PI3K/Akt pathway in B-cell chronic lymphocytic leukemia (B-CLL)." (PMID 35743222, 2022). "Ligation of CD180 in chronic lymphocytic leukemia B cells leads to the activation of BTK/PI3K/AKT or p38 MAPK pathways and both pathways have been shown to affect the activity of NF-κB." (PMID 33809015, 2021). "The MyD88-independent pathways of CD180 signaling under pathologic conditions has only been investigated in chronic lymphocytic leukemia cells showing the activation of BTK/PI3K/AKT or p38 MAPK pathways." (PMID 33809015, 2021). "SLAMF1 and CD180 are considered positive CD20 expression regulators that may promote the responsiveness of SLAMF1+CD180+ B cell CLL to cancer immunotherapies based on CD20 targeted therapy." (PMID 37251372, 2023).
osteosarcoma (4 papers, 2020 to 2023). A usually aggressive malignant bone-forming mesenchymal neoplasm, predominantly affecting adolescents and young adults. "Recently, it has been found that the risk model composed of CD180, MYC, PROSER2, and FATE1 has a great fitting effect on the overall lifetime of osteosarcoma." (PMID 34488541, 2021). "Levels of CD180 mRNA are upregulated in patients with osteosarcoma with superior outcomes." (PMID 37460961, 2023). "Finally, a 5-gene prognostic model consisting of COL13A1, TNFRSF1A, LILRA6, CTNNBIP1, and CD180 was established for predicting the prognosis of osteosarcoma." (PMID 36035315, 2022). "Among them, five genes, including CD180, MYC, PROSER2, DNAI1, and FATE1, with significant contribution to the model were selected as the candidate genes in the optimal prognostic risk model of osteosarcoma." (PMID 33082842, 2020).
ischemia (2 papers, 2018 to 2023). A hypoperfusion of the BLOOD through an organ or tissue caused by a PATHOLOGIC CONSTRICTION or obstruction of its BLOOD VESSELS, or an absence of BLOOD CIRCULATION. "Multiple microRNAs, including miR-141-p, miR-327, and miR-383, can interfere with CD180 expression and inhibition of these microRNAs can ameliorate cardiac tissue damage in ischemia models." (PMID 37460961, 2023). "The protective effect of CD180 in ischemia could be dampened through the interference of microRNAs, which are involved heavily in cardiovascular pathologies." (PMID 37460961, 2023). "Building on this work, it was shown that CD180 overexpression can ameliorate cardiomyocyte apoptosis via inhibition of TLR4 signaling and p38MAPK phosphorylation signalin ischemia/reperfusion injury rat models." (PMID 37460961, 2023). "Moreover, in cardiomyocytes, CD180 was able to effectively reduce TLR4-mediated production of pro-inflammatory IL-6 and TNF-α in response to ischemia." (PMID 37460961, 2023). "Also, lack of CD180, a specific inhibitor of the TLR4-mediated inflammatory response, accelerated inflammation and retarded blood flow recovery after ischemia." (PMID 30460242, 2018).
lymphoma (2 papers, 2021 to 2023). A malignant (clonal) proliferation of B- lymphocytes or T- lymphocytes which involves the lymph nodes, bone marrow and/or extranodal sites. "A multicentre study suggested that the high density of CD180 in marginal zone lymphoma (MZL) can be used in a test panel as a marker to distinguish MZL from other lymphomas and leukemias with similar characteristics." (PMID 37460961, 2023). "In both leukemia and lymphomas, the patterns of CD180 expression are heterogenous." (PMID 37460961, 2023). "The addition of CD180 in the flow cytometry and immunohistochemistry panel has made it possible to better classify these lymphomas with sensitivity and specificity evaluated at least at 75% and 90%, respectively, making CD180 a helpful immunologic marker in MZL." (PMID 34590593, 2021). "Moreover, the intensity of CD180 staining may favor a splenic origin of the lymphoma, as SMZL and SDRPL display particularly high levels of CD180 expression in flow cytometry." (PMID 34590593, 2021).
myasthenia gravis (2 papers, 2021 to 2025). Myasthenia gravis (MG) is a rare, clinically heterogeneous, autoimmune disorder of the neuromuscular junction characterized by fatigable weakness of voluntary muscles. "Collectively, our results suggest that interferon regulatory factor 1 enhances T cell differentiation by recruiting histone deacetylase 1 to block B cell CD180 transcription in myasthenia gravis via the Toll-like receptor 4/mitogenactivated protein kinases/nuclear factor-kappa B pathway." (PMID 41169211, 2025). "Evaluating disease severity by the Quantitative Myasthenia Gravis (QMG) score, the CD180 negative B cells correlated with disease severity (R2 = 0.30, P = 0.025) in MG patients." (PMID 34521820, 2021).
Sepsis (2 papers, 2011 to 2023). Sepsis is defined as life-threatening organ dysfunction caused by a dysregulated host response to infection. "Therefore, the upregulation of CD180 could serve to prevent hyperinflammation during infection, thereby preventing sepsis." (PMID 37460961, 2023).
Sjögren's syndrome (2 papers, 2021 to 2023). "Increased proportion of CD180-negative B cells was described in SLE and Sjögren's syndrome, and we previously reported significantly decreased expression of CD180 in B cells of dcSSc patients." (PMID 34124274, 2021).
uveitis (2 papers, 2020 to 2025). An inflammatory process affecting a part of or the entire uvea. "Machine learning identified IFN-associated genes as robust predictors, while linear discriminant analysis pinpointed CCR2, CD180, GAPT, and PTGS2 as key risk factors in isolated uveitis and CA1, SIAH2, and PGS in systemic disease-associated uveitis." (PMID 40270958, 2025). "The genes that showed a significantly increased risk ratio for uveitis in the uveitis only group, and were upregulated in patients, included CCR2, CD180, GAPT, and PTGS2." (PMID 40270958, 2025). "Cluster 3 (C3) represented a gene signature associated with uveitis that includes core B cell genes, including the MS4A1 gene (encoding CD20), Toll-Like Receptors (TLR) TLR7 and CD180 that regulates B cells responses, and ITSN2 a key gene required for antibody formation in B cells." (PMID 33042130, 2020). "For instance, in the uveitis only group, the genes KLHL21, MYLIP, ZNFX1, PDE4A, TNFRSF21, and N4BP2L2 were downregulated, while METTL72, GAPT, CD180, CCR2, and TLR7 were upregulated when comparing uveitis patients with healthy controls." (PMID 40270958, 2025). "For instance, metaDEGs of the uveitis only group comprise genes that are involved in the innate immune response, such as chemokine receptors (CX3CR1, CCR1, and CCR2), and Toll-like receptors (TLR4, TLR7, TLR8, and the TLR4 homologous receptor, CD180)." (PMID 40270958, 2025).
viral infection (2 papers, 2012 to 2023). "However, CD180 expression was upregulated on KD B cells compared to normal controls and those with viral infections." (PMID 37460961, 2023). "Given the upregulation of CD180 in both KD and viral infection, analysing changes in CD180 expression may be useful for predicting which individuals may present with Kawasaki-like disease or systemic inflammation in SARS-CoV-2 infection." (PMID 37460961, 2023). "Notably, patients with viral infections similarly exhibit upregulated proportions of CD180-positive B cells, although to a lesser degree, further indicating a link between viral infection and KD." (PMID 37460961, 2023). "Furthermore, there is a report of increased expression of CD180, which is regarded as a B-cell surface TLRs homologue, in viral infection and a Kawasaki disease patient." (PMID 22830029, 2012).
acute myeloid leukemia (1 paper, 2023). Acute myeloid leukemia (AML) is a group of neoplasms arising from precursor cells committed to the myeloid cell-line differentiation. "CD180 appears to be mainly confined to malignancies of the B cell lineage with only one report on acute myeloid leukemia which demonstrated that CD180 gene expression is high in leukemic stem cells." (PMID 37460961, 2023).
atherosclerosis (1 paper, 2024). A disease characterized by the build-up of fatty material and calcium deposition in the arterial wall resulting in partial or complete occlusion of the arterial lumen. "As TLR4 is a common precipitator of inflammation in microbial infection, atherosclerosis, and vascular remodelling, they targeted a known regulator on inflammatory immune cells and VSMCs called RP105 (also known as CD180)." (PMID 39404400, 2024).
bone metabolic disorders (1 paper, 2021). "As a non-canonical member of the TLRs, radioprotective 105 kDa (RP105 or CD180) and its ligand, myeloid differentiation protein 1 (MD1), are involved in several bone metabolic disorders." (PMID 34414191, 2021).
common variable immunodeficiency (1 paper, 2018). "RA has been shown to normalize the proliferation of defective B cells and restore their IgG-producing capacities as well as IL-10 production in the presence of TLR9/CD180 stimulation in common variable immunodeficiency (CVID) models." (PMID 30081517, 2018).
esophageal squamous cell carcinoma (1 paper, 2024). Esophageal squamous cell carcinoma (ESCC) is a type of esophageal carcinoma (EC) that can affect any part of the esophagus, but is usually located in the upper or middle third. "CD180 has also been identified as a prognostic biomarker in hematological malignancies and esophageal squamous cell carcinoma." (PMID 39707188, 2024).